IGLON5 (IgLON family member 5)
Diseases named in the same sentence as IGLON5 in open-access papers (continued):
Sharing a sentence is not in itself a finding about the gene and the disease.
sleep disorder (23 papers, 2020 to 2026). A change from the patient's baseline sleeping pattern, in the hours slept and/or an alteration/dysfunction in the stages of sleep. "Anti-IgLON5 disease is a recently discovered autoimmune encephalopathy with sleep disorder as a hallmark in the majority of reported cases." (PMID 38450066, 2024). "IgLON5‐associated autoimmunity was first described as a central nervous system disorder with typical sleep disturbances." (PMID 36698996, 2022). "Sleep disorders have recently been described in association with a number of autoantibody-associated CNS disorders, including anti-IgLON5, anti-DPPX, anti-CASPR2 and anti-NMDAR encephalitis." (PMID 35907972, 2022). "Anti-IgLON5 disease is a rare autoimmune neurological disorder characterized by sleep disturbances, movement disorders, cognitive decline, bulbar symptoms, and respiratory dysfunction, with a complex interplay between autoimmunity and neurodegeneration." (PMID 41808898, 2026). "IgLON5 has a variable presentation, with sleep disorder, bulbar symptoms, gait abnormalities, and cognitive dysfunction being the most prevalent." (PMID 41445985, 2025). "These motor features of anti-IgLON5 disease are frequently accompanied by sleep disturbances, bulbar symptoms, and neuropsychiatric changes, all signs that can be found in CNS-WhD too." (PMID 41245003, 2025). "In 2021, 5 patients with a bulbar onset motor neuronopathy were found having serum IgLON5 antibodies, 4/5 patients having a coexisting sleep disorder." (PMID 39555481, 2024). "Results indicate that most of the patients affected with anti-IgLON5, experience sleep disorders to an extent that forces them to look for medical help." (PMID 35300333, 2022). "It appears that anti-IgLON5 has a distinctive sleep disorder pattern which is unique to this disease." (PMID 35300333, 2022). "Reports of sleep disorders in anti‐IgLON5 disease particularly comprise sleep‐related vocalizations, movements or behaviors, and sleep disordered breathing with obstructive sleep apnea syndrome, stridor or central hypoventilation." (PMID 36698996, 2022). "Due to the fact that sleep disorder is one of the most characteristic abnormalities in anti-IgLON5 disease, video polysomnography (VPSG) should be performed in any suspected case of this condition, not only on patients who complain of sleep problems." (PMID 35300333, 2022). "Although sleep disorder, bulbar symptoms and gait abnormality form the main symptoms of anti-IgLON5 disease, they can differ in severity and onset, making various combinations with other clinical features present." (PMID 35300333, 2022). "When a patient presents with heterogeneous neurological symptoms including distinctive sleep disorders often accompanied by bulbar symptoms, gait instability or cognitive deterioration, anti-IgLON5 disease should always be suspected." (PMID 35300333, 2022). "Anti-IgLON5 sleep disorder can be characterized by abnormal NREM sleep initiation, rapid eye movement sleep behavior disorder (RBD), motor activation and breathing problems such as stridor and apnea." (PMID 35300333, 2022). "In the largest case series of patients with anti‐IgLON5 disease published to date, sleep disorders were present in nearly 90% of patients at the time of diagnosis." (PMID 36698996, 2022). "Testing for IgLON5-antibodies should be considered in patients with progressing cognitive decline, especially if accompanied by sleep disorders or neurological symptoms like oculomotor abnormalities, dysautonomia or bulbar signs." (PMID 33633675, 2021). "Patients diagnosed with anti-IgLON5 disease appear to have four core syndromes: 1) sleep disorder 2) bulbar dysfunction 3) progressive supranuclear palsy (PSP) - like syndrome 4) cognitive impairment." (PMID 34659261, 2021). "Anti-IgLON5 disease usually differs from PSP in typical sleep disorders, although one in two patients has supranuclear gaze palsy or other symptoms that mimic atypical Parkinson’s syndrome." (PMID 34659261, 2021).
sleep disorder (continued). "Very rarely, it has been reported in patients with IgLON5 autoantibodies, usually in combination with a distinct sleep disorder, bulbar dysfunction and gait abnormalities." (PMID 33324912, 2020). "On the other hand, some sleep disorders may have a diagnostic role in some specific AIE, or even play a crucial role in the recognition of AIE, like anti-IgLON5 disease." (PMID 38913197, 2024). "Signs of episodic pelvic limb paresis in the IgLON5 AB‐positive dog occurred only in temporal context with sleep, that is, on awakening or associated with paradoxical arousal which is to some degree reminiscent of the frequent reports of sleep disorders in humans with IgLON5 antibodies." (PMID 37232512, 2023). "This case report suggests that anti‐IgLON5 disease should be considered in patients presenting with adult onset hemichorea, even in the absence of typical sleep disorders associated with anti‐IgLON5 disease." (PMID 36698996, 2022). "Furthermore, PSG‐verified sleep disorders in anti‐IgLON5 disease can be more discrete than the typically described parasomnias or sleep‐related breathing disorders and only present as periodic limb movements during sleep." (PMID 36698996, 2022). "Besides sleep disorders, gait problems, bulbar dysfunction and movement disorders, with chorea being reported in about a third of patients, dysautonomia, neurocognitive deficits and behavioral symptoms represent other common features in anti‐IgLON5 disease." (PMID 36698996, 2022). "Concerning the reports of sleep disorders, it is of utmost importance to note that sleep abnormalities are often not evaluated by the treating physician at initial presentation, which could result in an insufficient recognition of this characteristic feature in anti‐IgLON5 disease." (PMID 36698996, 2022). "We also found IgLON5 antibodies in one control dog without any signs of epileptic seizures, movement, or sleep disorder on questioning of the dog owner." (PMID 37232512, 2023). "Sleep disorders, indeed, are a milestone of anti‐IgLON5 disease; however, this is not the main reason for an initial consultation in most patients; instead, gait problems, bulbar dysfunction or movement disorders are." (PMID 36698996, 2022). "Sleep disorders were prevalent among the cohort (28 patients, 29%) and included central sleep apnea (12, 12%), insomnia (10, 10%), REM sleep disorder (10, 5 of whom were IgLON5‐IgG positive), hypersomnia (6, 6%), and narcolepsy/cataplexy (3, 2 of whom had Ma2‐IgG)." (PMID 39708293, 2025). "Furthermore, this study did not investigate the mechanisms of sleep disorders in anti-IgLON5 disease." (PMID 37760924, 2023). "Ig-like cell adhesion molecule 5 (IgLON5) antibodies have been first described in 2014 in patients presenting with sleep apnea, REM-sleep or non-REM-sleep disorders." (PMID 39555481, 2024).
tauopathy (19 papers, 2016 to 2026). Neurodegenerative disorders involving deposition of abnormal tau protein isoforms (tau proteins) in neurons and glial cells in the brain. "The limited knowledge of the physiological function of IgLON5 represents a major drawback to studying the pathogenic mechanisms of IgLON5 antibodies and the relation with the tauopathy observed in some patients." (PMID 38370417, 2024). "In the current study, we investigated post-mortem brain tissue of nine anti-IgLON5 patients to characterize the cellular and humoral inflammation and the spectrum of IgLON5-antibody-associated tauopathy." (PMID 37646790, 2023). "Anti-IgLON5 disease is a rare neurological, probably autoimmune, disorder associated in many cases with a specific tauopathy." (PMID 37646790, 2023). "We report here the main neuropathological features underlying the anti-IgLON5 syndrome that are different from those of other tauopathies." (PMID 27358064, 2016). "Based on the similarities of these cases we propose research criteria for the neuropathological diagnosis of the tauopathy underlying the anti-IgLON5 syndrome and recommend a protocol of tissue sampling." (PMID 27358064, 2016). "We propose that the tauopathy underlying the anti-IgLON5 syndrome can be diagnosed with three levels of probability: definite, probable, and possible." (PMID 27358064, 2016). "Anti- IgLON5-related tauopathy is strongly associated with two specific HLA types, and different HLA types reflecting individual susceptibility or immune responses might also be responsible for the complex relationship between EL and PEP." (PMID 34442795, 2021). "We then examine the underlying immunopathophysiology, which may guide treatment decisions in these neuroimmunological disorders, and highlight the exceptional interface between neuronal antibodies and neurodegeneration, such as the tauopathy associated with IgLON5 antibodies." (PMID 29053777, 2018). "Anti-IgLON5 disease is a rare neuroimmunological condition with overlapping features of autoimmunity and tauopathy, manifesting with sleep and cognitive disturbances, bulbar symptoms, and movement disorders." (PMID 41993784, 2026). "Importantly, IgLON5-Ab patients were found to have a significantly higher frequency of the H1/H1 genotype compared to healthy controls, hinting to an underlying susceptibility to develop the well-known tauopathy of IgLON5-Ab disease, possibly triggered by the inflammatory response." (PMID 40274643, 2025). "Anti-IgLON5 antibody-related encephalitis is a secondary tauopathy stands at a critical juncture of autoimmunity and neurodegeneration, where deposition of hyperphosphorylated tau occurs mainly in the hypothalamus, brainstem, and hippocampus." (PMID 38765268, 2024). "Based on these findings, and the experimental data supporting that the tauopathy is a secondary event of the autoimmune disorder, we suggest a classification into three pathological stages of the anti-IgLON5 disease-related tauopathy." (PMID 39400557, 2024). "We present new neuropathological observations in a larger autopsy series of 22 patients affected by anti-IgLON5 disease and propose adaptation the original neuropathological research criteria of its unique tauopathy based on the new findings." (PMID 39400557, 2024). "At this stage of pathology, all areas reported in the original description of the anti-IgLON5 disease-related tauopathy are severely affected and show high burden of tau pathology (Figs. 1b3, d3, f3, 3)." (PMID 39400557, 2024). "The distribution of PSP pathology, particularly in the brainstem, has overlapping features with the classical anti-IgLON5-related tauopathy and has to be considered in the differential diagnosis." (PMID 37646790, 2023). "In our patient, only the affection of the synaptic glomerula of the cerebellar cortex was unusual for PSP and suggests an overlap with classical anti-IgLON5 related tauopathy, where this feature has been reported." (PMID 37646790, 2023).
tauopathy (continued). "The originally described anti-IgLON5-related tauopathy has been defined as mostly restricted to neurons and characterized by a mixture of 3R and 4R tau pathology." (PMID 37646790, 2023). "Secondary tauopathies describe disorders that require additional etiologies such as Aβ deposition (i.e., AD), repeated head trauma (i.e., CTE), or autoimmunity (e.g., anti-IgLON5-related tauopathy) for tau deposition." (PMID 35806324, 2022). "An immune-triggered phospho-tau formation has recently been shown in anti-IgLON5-related tauopathy, a parasomnia with bulbar dysfunction due to an autoantibody against a neuronal cell-adhesion molecule." (PMID 34442795, 2021). "Anti IgLON5 mediated secondary tauopathy stands at a critical juncture of autoimmunity and neurodegeneration, where deposition of hyperphosphorylated tau (both 3R and 4R) occurs mainly in the hypothalamus, brainstem, and hippocampus." (PMID 33250855, 2020). "While secondary tauopathy from autoimmune insult like in anti-IgLON5 disease brings up the topic of complex interaction between autoimmunity and neurodegeneration, geographically isolated tauopathies highlight the environmental impact." (PMID 33250855, 2020). "IgLON family member 5 (IgLON5) antibodies are found in the serum and CSF of patients with postmortem evidence of a tauopathy." (PMID 30218501, 2018). "The recent discovery of neuronal surface antibodies against IgLON5 in defining a novel tauopathy has more closely apposed the boundaries between neurodegeneration and neuroimmunology." (PMID 29053777, 2018). "A “definite” diagnosis of anti-IgLON5-related tauopathy is established when these neuropathological features are present along with the detection of serum or CSF IgLON5 antibodies." (PMID 27358064, 2016). "We suggest including these cases under the umbrella term of a single clinicopathological entity termed “anti-IgLON5-related tauopathy”." (PMID 27358064, 2016). "When a neuropathologist is confronted with a case with such a neuropathological phenotype in conjunction with positive IgLON5 antibodies in CSF or serum, the diagnosis of “definite anti-IgLON5-related tauopathy” should be considered." (PMID 27358064, 2016). "Anti-IgLON5 disease not only has antibodies against the IgLON5 protein but also shows a deposition of hyperphosphorylated tau in the tegmentum of the brainstem and hypothalamus, leading to progressive neurodegeneration similar to other tauopathies such as PSP." (PMID 41445985, 2025). "Second, we have observed concomitant TDP-43 protein aggregates (neuronal and fewer oligodendroglial) in about one-third of cases with anti-IgLON5 disease, associated or not with the extensive tauopathy." (PMID 39400557, 2024). "Finally, we suggest to adapt the diagnostic categories of the original neuropathological research criteria of the anti-IgLON5 disease-related tauopathy according to the new observations in this larger autopsy series." (PMID 39400557, 2024). "Finally, we adapt the original research criteria of the anti-IgLON5 disease-related tauopathy to include the spectrum of pathologies observed in this larger postmortem series." (PMID 39400557, 2024). "The classical risk HLA haplotype DRB1*10:01 and DQB1*05:01 did not associate with the IgLON5 tauopathy as it was present in three patients with and two without the classical anti-IgLON5-related tauopathy." (PMID 37646790, 2023). "Tau pathology: Five cases (55.5%, four previously published) showed the already described 3R-tau and 4R-tau pathology with tau-positive neuronal inclusions mainly in hypothalamus and tegmentum of the brainstem, according to the neuropathological criteria of anti-IgLON5-related tauopathy." (PMID 37646790, 2023). "Distinct localization of tau-deposits compared to that found in another neurodegenerative diseases, e.g. Progressive Supranuclear Palsy (PSP) and Corticobasal Syndrome (CBS), could indicate that anti-IgLON5 is a novel tauopathy." (PMID 35300333, 2022).
tauopathy (continued). "More neuropathological studies are needed to clarify whether the hippocampal involvement in our patients indicates the presence of an associated PART as an accelerated aging or is part of the neuropathological signature of anti-IgLON5-related tauopathy." (PMID 27358064, 2016). "However, how the blocking of IgLON5 interferes with downstream signal transduction pathways that may result in tauopathy is still unclear." (PMID 37646790, 2023). "In contrast, when the information of the anti-IgLON5 antibodies status is missing but the clinical history is compatible or the patient harbored the HLA-DRB1*1001 and HLA-DQB1*0501 alleles, then the diagnostic category of “probable anti-IgLON5-related tauopathy” should be applied." (PMID 27358064, 2016). "The topographical distribution of the tau pathology is similar to that seen in another tauopathy, progressive supra-nuclear palsy (PSP); however, the absence of glial pathology and sparse supratentorial and basal ganglia involvement in IgLON5-IgG disease is distinct." (PMID 39063198, 2024). "In contrast, we found an extensive neuropil deposition of IgG4 in the tegmentum of the brainstem, olivary nucleus, and cerebellar cortex that was most prominent in two patients with short disease duration without the typical IgLON5-related tauopathy." (PMID 37646790, 2023). "Inflammatory infiltrates of T and B cells were mild to moderate and did not significantly differ between anti-IgLON5 disease cases with or without tauopathy." (PMID 37646790, 2023). "However, the IgLON5-KO mouse model does not reproduce the clinical phenotype or the tauopathy reported in anti-IgLON5 disease." (PMID 38370417, 2024). "In contrast, 7/22 cases (32%) did not meet the neuropathological criteria of the anti-IgLON5 disease-related tauopathy due to the lack of overt/prominent brainstem tau pathology, although patients had the clinical features of anti-IgLON5 disease and had anti-IgLON5 antibodies." (PMID 39400557, 2024). "Inflammatory infiltrates could not be evaluated in patient 8, who presented a tauopathy suggestive of anti-IgLON5 disease but IgLON5 antibodies could not be evaluated." (PMID 37646790, 2023). "Immunotherapy is the cornerstone for addressing the inflammatory component of IgLON5-IgG disease as there are currently no effective treatments for the neurodegenerative component though putative therapeutic targets have been identified in the context of other tauopathies." (PMID 39063198, 2024). "One of our main immunological findings is that two patients with anti-IgLON5 disease without brainstem tauopathy had an intense deposition of IgG4 in the neuropil and along the membrane of neurons in the tegmentum of the brainstem, olivary nuclei, and cerebellar cortex that co-localized with IgLON5." (PMID 37646790, 2023). "Alternatively, the anti-GlyR antibodies might have developed secondarily to neurodegeneration (most likely a 4-repeat tauopathy, PSP or CBD) without exerting overt clinical effects, as in cases of anti-IgLON5 encephalopathy." (PMID 32585946, 2020).